TNF (tumor necrosis factor)
Diseases named in the same sentence as TNF in open-access papers (continued):
Sharing a sentence is not in itself a finding about the gene and the disease.
cancer (continued). "In addition, it is known that fusion of cancer cells with macrophages or MSC can be induced by pro-inflammatory cytokine tumor necrosis factor-α (TNF-α)." (PMID 36555709, 2022). "This study showed that MSM improved the inflammatory response of UC via the IL-17 and TNF signaling pathways, which may prove beneficial to alleviate symptoms and prevent cancer." (PMID 35966251, 2022). "It has been suggested that the properties of TNF contributing to the death of neoplastic cells may constitute a potential cancer therapy." (PMID 36289922, 2022). "For cancer-elicited intrinsic inflammation, puerarin was able to regulate macrophage polarization and the expression of proinflammatory cytokines and genes, including TNF-α, IL-12, NF-κB, and TLR4." (PMID 35935578, 2022). "This and further mechanisms result in the release of multiple inflammatory cytokines from reactive astrocytes, including IL1β, IL6, IL8, IFNα, or TNFα, which then drive the survival and colonization of cancer cells, as well as chemo‐resistance through calcium sequestration." (PMID 35506376, 2022). "Surprisingly, TNF-α expression increases from hyperplasia to carcinoma, and also during TNM stages in GBC tissues, suggesting that TNF-α could participate in carcinogenic processes and may be a progression marker in GBC patients." (PMID 35207722, 2022). "Since the major increase in IL-33 in the Gem+ICB+CCR2i group was observed from carcinoma cells, we sought to test whether TNF-α can directly regulate IL-33 expression in carcinoma cells." (PMID 36256464, 2022). "Our study suggests that TNF-α directly regulates the expression of IL-33 in carcinoma cells, thus supporting the conclusion that TNF-α plays a role in immune suppression in PDA that can be overcome through blockade of bone marrow–derived macrophages in concert with immune therapy." (PMID 36256464, 2022). "On the other hand, increased level of fibrinolysis and coagulation could become the soil for cancer growth, via secretion of cytokines and chemokines (including TNF, NF-KB, and macrophage inflammatory protein-1), as well as activation of macrophages." (PMID 34404438, 2021). "Several fusion proteins containing TNF-α have been designed as a cancer treatment." (PMID 33801589, 2021). "In addition, the interaction between NF-κB and proinflammatory cytokines such as TNF-α and IL-1β is also involved in stimulating cancer cell proliferation, especially during chronic inflammation." (PMID 34079469, 2021). "Hence, we aim to target the signaling pathways which are involved in the initiation of cancer such as NFƙB, TNF-α, and IFN-γ." (PMID 33928164, 2021). "sEVs harvested from raw bovine milk loaded with a mixture of cyanidin, delphinidin, petunidin, peonidin and malvidin increase the anti-proliferative activity of anthocyanidins against six different types of cancer cells via the inhibition of TNFα-induced activation of NF-κB." (PMID 34959929, 2021). "Even though the known functional role of AWP1 (zinc finger AN1 type-6, ZFAND6) is as a key mediator of TNF-α signaling, its potential role in the TNF-α-dependent responses of cancer cells remains unclear." (PMID 33816268, 2021). "TNF also induces the formation of cancer stem-like phenotypes in oral squamous cell carcinoma." (PMID 34307156, 2021). "TNF-α is a pleiotropic cytokine that shows a dual role in cancer progression." (PMID 33461943, 2021). "The elevated expression level of GSDMC, which could be induced by the nuclear translocated PD-L1, is required for the switching TNFα-induced apoptosis to pyroptosis in cancer cells." (PMID 34421915, 2021). "TNF plays an important role in human cancer development and progression and may serve as a prognostic factor." (PMID 33917839, 2021).
cancer (continued). "The therapeutic potential of Ni was tested in in vitro models of sarcopenia (dexamethasone-induced myotube atrophy), cancer cachexia (tumor necrosis factor-α treated myotubes) and myogenesis, in addition to an animal model of dexamethasone-induced skeletal muscle atrophy." (PMID 34038481, 2021). "TNF, BRCA2, MYC, and IL6 are some examples of proteins that are frequently associated with PCa and are also known to function as biomarkers for other types of cancer." (PMID 34771740, 2021). "TNF-alpha activates NF- kappa beta signaling, thereby contributing to inflammation, cell survival, proliferation, The transcription factor NF- kappa beta links inflammatory signaling and cancer." (PMID 35008550, 2021). "Consequently, failure to release TNF or impaired cytotoxic TNF signaling renders cancer cells resistant to SM." (PMID 33484626, 2021). "Therefore, it is regarded as a potential target for cancer therapeutics, particularly those cancers that are human epidermal growth factor (EGFR) receptor (EGFR) ligands or TNF-alpha positive." (PMID 34441816, 2021). "In contrast to this beneficial acute spike in cytokines, a meta-analysis of current literature shows that long-term ET results in decreased systemic inflammation in cancer survivors evidenced by reduced C-reactive protein and TNF-α, with the strongest effects in breast and prostate cancer." (PMID 33801684, 2021). "Further analysis of the PSOLAR registry analyzed the risk of malignancy with TNF-α inhibitor therapy compared to methotrexate and ustekinumab in patients with no history of cancer." (PMID 34884596, 2021). "The inflammatory processes exacerbated by cytokines TNF-α and IL-1β are key events in IVDD, they contribute to IVDD through degradation of extracellular matrix, and they are implicated in wounds and cancer." (PMID 33579726, 2021). "Indeed, many naturally occurring and synthetic compounds are able to sensitize cancer cells to TNF-induced cell death by inhibiting NF-κB activity." (PMID 34025421, 2021). "For DEG enrichment analysis, immune-related pathway (such as IL-17 signaling pathway and TNF signaling pathway), cancer-related pathway, and DNA-related pathway were shown, and it could be correlated with prognosis." (PMID 34646755, 2021). "The antitumor activities of TNF-α have been leveraged in cancer treatments." (PMID 33429846, 2021). "Given that EMT plays crucial roles in cancer cell migration, we examined whether the TNF-α-mediated enhancement of the expression of EMT-related genes in AWP1 KO cells could be inhibited by NAC." (PMID 33816268, 2021). "Whilst we are interested in developing TNFα-CSG as an anti-cancer therapeutic, as an imaging agent, CSG-IO-NP may be used for diagnostic screening to identify patients who may benefit from TNFα-CSG therapy." (PMID 34683956, 2021). "With the progress of research in patients with chronic inflammatory diseases, many mechanisms of TNF antagonist therapy in inhibiting TNF-enhanced cancer development have been found: angiogenesis, leukocyte infiltration, and stimulation of other cytokines and chemokines." (PMID 34079469, 2021). "Therefore, as a scientific approach to cancer cachexia, many attempts have been made to inhibit cancer cachexia by targeting the inflammatory cytokines, tumor necrosis factor alpha (TNF-α) and interleukin (IL)-6." (PMID 34262449, 2021). "Inflammatory macrophages play an important role in cancer initiation by creating a mutagenic micro-environment through producing proinflammatory mediators, such as IL-6, TNFα, and interferon-gamma (IFNγ); as well as growth factors, including epidermal growth factor (EGF) and metabolites." (PMID 34207286, 2021). "Interestingly, TNF plays a “double-edged sword” role in cancer, largely depending on the role of TNF-R1 and TNF-R2." (PMID 34630563, 2021). "LPS activates TNFα, leading to inflammation-induced cancer cell proliferation." (PMID 34830441, 2021). "In both cases, SM sensitize cancer cells to TNF‐dependent killing." (PMID 33484626, 2021).
cancer (continued). "Researches showed editing role in the pathogenesis of cancer and indicated its relation with mediators such as tumour necrosis factor-α (TNF-α), soluble TNF-related apoptosis-inducing ligand (sTRAIL), interleukin-6 (IL-6), pentraxin-3 (PTX-3), procalcitonin (PCT), and Creactive protein (CRP) levels." (PMID 33776564, 2021). "Cancer promotion can be regulated by several pathways associated with inflammation, such as those involving NF-κB, STAT3, mTOR, and MAPKs, which are triggered by pro-inflammatory cytokines like IL-6, TNF-α, and IL-1β." (PMID 34950252, 2021). "This has been previously established; however, this study shows that the recruitment of MDSCs by cancer cell-derived IL-1β and TNF secretion could aid in PMN angiogenesis by revealing a number of pro-angiogenic factors secreted by MDSCs, including MMP-9131." (PMID 33659922, 2021). "Cancer cell activation also can be induced by numerous agents, including TNF-α." (PMID 33953676, 2021). "Similarly, excluding the irrelevant pathways, KEGG analysis showed several representative enriched pathways of DEmRNAs, including the TNF signaling pathway, IL-17 signaling pathway, and microRNAs in cancer." (PMID 34440578, 2021). "This differential blockade of TNFα isoforms is critical for activating the immune system in cancer patients, since it is known that the tmTNFα–TNFR2 interaction is necessary for the crosstalk between DC and NK cells, which does not depend on the sTNFα-TNFR1 axis." (PMID 33540543, 2021). "In inflammation and cancer, TNF‐α inhibits the activity of PPARγ via IκBα‐mediated signalling." (PMID 34302428, 2021). "Psychosocial stressors in cancer promote inflammation and oxidative/nitrosative stress, with alterations in cytokine secretion and regulation (TNF-a or Il-6); decreased immunosurveillance; dysfunctional activation of the autonomic nervous system and hypothalamic–pituitary–adrenal axis." (PMID 35008225, 2021). "In this section, we outline the different cancer therapies based on mAbs targeting cancer cells and, in the following section, the mAbs directed to immune checkpoints, highlighting the implications of combining them with TNFα blocking agents." (PMID 33540543, 2021). "Furthermore, TNF-α induces metabolic changes in lipid metabolism, which are typical of advanced cancer patients, particularly those with cachexia." (PMID 33535496, 2021). "TAM favors CCL20 production by cancer cells through their secretion of TNF-α, IL-1β and IL-6." (PMID 33924428, 2021). "For instance, anti-tumor necrosis factor (TNF) treatment without an immunomodulator does not increase cancer risk in patients with IBD." (PMID 33849449, 2021). "Even better than IL-6, TNF-α is a key inflammatory cytokine in cancer cachexia." (PMID 34262449, 2021). "Furthermore, these exosomes presented FasL, perforin and TNF-α, which are well known to be involved in NK cell-mediated cancer killing." (PMID 33530529, 2021). "Genetic comorbidities involving TNF-α pathway have also been reported, as it was found that RA patients bearing GG homozygosity at the TRAF1-C5 SNP rs3761847 were at a higher risk of death from cancer or sepsis." (PMID 34201546, 2021). "Animal models have suggested that TNF antagonists may prevent the development or progression of dysplasia and cancer, and some population-based data within IBD have demonstrated a lower frequency of CRC among those treated with infliximab." (PMID 34063506, 2021). "These circSlc7a11-regulated mRNAs were also involved in many signaling pathways, including RIG-I-like receptor signaling, chemokine signaling, Toll-like receptor signaling, TNF signaling, GnRH signaling, as well as pathways involved in cancer, influenza A, and pyrimidine metabolism." (PMID 33433832, 2021).
cancer (continued). "Consistent with this concept, our results indicate that TPH104 not only killed MDA-MB-231 cells via a non-apoptotic pathway but also caused ICD, accompanied by the release of the pro-inflammatory mediator TNFα, to increase the adaptive immune response against cancer cells." (PMID 33919653, 2021). "NF-κB, in turn, is a key effector of TNF in inflammation-induced cancer." (PMID 33373873, 2021). "To further identify the potential soluble factors from MPE-Mφ-derived M1 macrophages might inhibit cancer cell growth, we performed experiments to examine the effects of M1-related cytokines (TNF-α, CXCL9, IFN-γ, or CCL3) on A549 cell proliferation." (PMID 33175182, 2021). "Additionally, these PPAR γ agonists have been reported to attenuate cancer-induced body weight wasting and TNF-α-induced adipocyte wasting." (PMID 34502316, 2021). "Cancer- or hypoxia-activated Schwann cells release nociceptive mediators such as IL-6, TNFα, CXCL2, and IL-811,15; these mediators could sensitize primary afferent neurons to cause pain." (PMID 33469141, 2021). "Our results suggest that AWP1 may act as an intracellular regulator of TNF-α-mediated cancer cell responses by regulating ROS/NF-κB activation." (PMID 33816268, 2021). "However, when administered to rats with cancer, safranal reduced both TNF-α level in serum and p-TNF-R1 expression in liver." (PMID 35177980, 2021). "The antitumor effect of macrophages includes the killing of cancer cells through both their own Fc receptors that bind antibodies on the surface of cancer cells and the production of nitric oxide (NO) and tumor necrosis factor (TNF)." (PMID 34298810, 2021). "Although the effects of TNF-α stimulation, such as activation of NF-κB, in cancer and other cells are well known, the mechanism by which it upregulates activity of the AP-1-related transcription factors in MCF-7 cells remains unclear." (PMID 34572567, 2021). "Previous studies have also demonstrated that cortisol, acting synergistically with catecholamines, may facilitate cancer cell growth and potentiate the release of TNF α and IL1 β." (PMID 33809172, 2021). "The factor that induced inflammation may be oxidative stress and may stimulate the production of proinflammatory cytokines, including interleukins (ILs) and TNF-α, which are involved in cancer development." (PMID 33923108, 2021). "In addition, we obtained drug screen data from the “Genomics of Drug Sensitivity in Cancer” database for two TNF pathway compounds that inhibit TRAF2 binding partners, BIRC2/BIRC3 (IAP-5620) and BIRC2 (AZD5582)." (PMID 33508232, 2021). "Although TNF-α is known to cause systemic inflammation, the selective and restricted activation of the TNF-α pathway in cancer cells, if achieved, could reprogram DCs in the TME to target cancer cells." (PMID 33919653, 2021). "Our study is one of a few to show FI and BI can induce TNF auto-secretion in cancer cells." (PMID 33542218, 2021). "The factors responsible for cancer cell proliferation may be a higher level of pro-inflammatory cytokines (TNF-α and CXCL8) and growth factors (VEGF, HCF, Ang-2, TGF-α, EPO, SCF, FGF, and PDGF-BB)." (PMID 34577154, 2021). "IL-32γ enhances the anti-cancer activity of TNF-α and blocks the NF-kB-STAT3 pathway." (PMID 34944856, 2021). "Another study demonstrated that the release of RAGE triggered by ferroptotic cells was necessary for HMGB1-mediated tumor necrosis factor (TNF) production in macrophages, suggesting that ferroptotic cancer cells could be immunogenic in nature." (PMID 33819918, 2021). "TNFα has a plethora of functions and implications, and this also applies to cancer cells." (PMID 33540543, 2021).
cancer (continued). "In addition, carnosine increases the secretion and gene expression of pro-inflammatory cytokine TNFα, a known anti-cancer agent with the capacity to induce cancer cell death." (PMID 33809496, 2021). "In all the three generations, the upregulated genes were enriched in the pathways that promoted cancer progression, like the Tumor Necrosis Factor (TNF) signaling pathway, cytokine receptor pathway, and Phosphatidylinositol 3-Kinas-Protein Kinase B (PI3-AKT) signaling pathway." (PMID 33803224, 2021). "Several studies have demonstrated that TNF-α induces phosphorylation of JNK, the JNK signal transduction pathway is associated with antioxidation and anti-inflammation, is usually upregulated in cancer cells." (PMID 34833849, 2021). "TNF-α has been reported to regulate cell cycle progression in different types of cancer cells." (PMID 35186944, 2021). "Moreover, contrary to the harmful effects of TNF cited above, when TNF is targeted to cancer endothelial cells in refractory NSCLC patients, there has been evidence of enhanced cisplatin toxicity." (PMID 34645978, 2021). "Research on bacterial immunotherapy may now avoid this side effect and allow TNF-α to be reapplied to cancer therapy." (PMID 34956913, 2021). "Similarly, positive correlations of PDL1 with cytokines such as TNFα and IL-6 have been reported in other chronic inflammatory diseases including systemic lupus erythematous and cancer." (PMID 34597347, 2021). "Surgical complications, mainly infections, induce excessive production of pro-inflammatory and inflammatory cytokines, such as tumor necrosis factor -alpha and interleukins 1 and 6, which may result in immune suppression promoting cancer growth and metastasis." (PMID 33799426, 2021). "The efficacy of TPH104 to induce the sustained production of TNF-α specifically by TNBC cells could be used as an adjuvant in cancer chemotherapy as this would decrease the magnitude of immunosuppression in the TME." (PMID 33919653, 2021). "Cancer cachexia is largely characterized by systemic inflammation, including increased proinflammatory cytokines such as interleukin 1 (IL-1), interleukin 6 (IL-6), or tumor necrosis factor α (TNFα)." (PMID 34945009, 2021). "Furthermore, a number of studies have identified an oncogenic role for TNF in inflammation related cancer." (PMID 33373873, 2021). "In addition, 43 KEGG pathways were significantly enriched for these genes, including hsa05200: pathways in cancer, hsa04668: TNF signaling pathway, hsa04010: MAPK signaling pathway, hsa04066: HIF-1 signaling pathway, and hsa04068: FoxO signaling pathway." (PMID 35087950, 2021). "Moreover, based on cancer research, body composition-based dosing regimens were also proposed for quinolones and anti-tumor necrosis factor medications." (PMID 34945089, 2021). "The 28 DEmRNAs were enriched in cancer-related pathways, for example, the TNF signaling pathway." (PMID 34093635, 2021). "The top five functional annotations were “PI3K-Akt signaling pathway” (P = 5.7E-4), “NF-kappa B signaling pathway” (P = 4.0E-3), “Transcriptional mis-regulation in cancer” (P = 5.2E-3), “TNF signaling pathway” (P = 8.2E-3), and “Insulin resistance” (P = 9.3E-3)." (PMID 33777102, 2021). "Notably, while C. rectus ESOS44-4 also upregulated TNF and IL-17 signaling, it significantly upregulated “Pathways in cancer” as well as “Transcriptional misregulation in cancer”." (PMID 34412659, 2021). "Numerous molecules such as tumor necrosis factor (TNF)-α, interleukin-1 (IL-1) and IL-6 are common biomarkers of inflammation associated with cancer, and they could be regulated by the transcription factor NF-κB." (PMID 35096970, 2021).